GULOP (gulonolactone (L-) oxidase, pseudogene)
Synonyms: GULO; scurvy
Gene: Unitary pseudogene on chromosome 8 (27,560,274 to 27,589,073, forward strand). Ensembl gene ENSG00000234770.
Diseases named in the same sentence as GULOP in open-access papers:
GULOP is named in the same sentence as 8 diseases in open-access papers, as found by Europe PMC text mining. Sharing a sentence is not in itself a finding about the gene and the disease.
GULOP shares sentences with these, for which no sentence is quoted: vitamin C deficiency (4 papers); Sepsis (2); tumor (2); anemia (1); breast carcinoma (1); Hepatic steatosis (1); hereditary spherocytosis (1); melanoma (1).